DDX60 (DExD/H-box helicase 60)
Description:
Positively regulates RIGI- and IFIH1/MDA5-dependent type I interferon and interferon inducible gene expression in response to viral infection. Binds ssRNA, dsRNA and dsDNA and can promote the binding of RIGI to dsRNA. Exhibits antiviral activity against hepatitis C virus and vesicular stomatitis virus (VSV). Selectively reduces infectious titers of viruses that depend on type II IRES-mediated translation by modulating ribosome occupancy on type II IRES-containing viral mRNAs, without affecting type I IRES-mediated translation.
Synonyms: FLJ20035
Tractability: PROTAC: ubiquitination databases record sites on it; its protein half-life has been measured.
Gene: Protein-coding gene on chromosome 4 (168,216,291 to 168,318,883, reverse strand). Ensembl gene ENSG00000137628.
Subcellular location: Cytoplasm
Subcellular location (Human Protein Atlas): Cytosol; Centrosome; Intermediate filaments
Gene Ontology:
Molecular function: double-stranded DNA binding; double-stranded RNA binding; protein binding; single-stranded RNA binding; ATP binding; ATP hydrolysis activity; nucleic acid binding; RNA helicase activity
Biological process: positive regulation of MDA-5 signaling pathway; positive regulation of RIG-I signaling pathway; response to virus; defense response to virus
Cellular component: cytoplasm; cytosol
Genetic constraint (gnomAD): Loss-of-function variants: 110 observed, 150.45 expected, observed/expected ratio (o/e) 0.73, 90% interval 0.63 to 0.86. The upper end of that interval is the gene's LOEUF score, 0.86, which puts it in group 3 of 6, group 1 being the genes least tolerant of losing a copy. Missense variants: 1,487 observed, 1,603.6 expected, observed/expected ratio (o/e) 0.93, 90% interval 0.89 to 0.97. Synonymous variants: 550 observed, 551.07 expected, observed/expected ratio (o/e) 1, 90% interval 0.93 to 1.07.
Homologues: Orthologues: chimpanzee DDX60 (99% identical), macaque DDX60 (96% identical), dog DDX60 (78% identical), rabbit DDX60 (78% identical), pig DDX60 (78% identical), mouse Ddx60 (75% identical), rat Ddx60 (74% identical), rat LOC134478918 (74% identical), guinea pig DDX60 (74% identical), tropical clawed frog ddx60 (50% identical). Paralogues in human: DDX60L (65% identical), ASCC3 (11% identical), HELQ (11% identical), SNRNP200 (11% identical), POLQ (10% identical), SKIC2 (10% identical), HFM1 (10% identical), MTREX (9% identical).
Diseases named in the same sentence as DDX60 in open-access papers:
DDX60 is named in the same sentence as 35 diseases in open-access papers, as found by Europe PMC text mining. Sharing a sentence is not in itself a finding about the gene and the disease. The quoted sentences say what the papers report.
viral infection (25 papers, 2015 to 2025). "For example, EGFR signaling limits antiviral activity associated with DDX60 (DExD/H-Box Helicase 60), an RNA helicase that recognizes short viral dsRNA in the cytosol during a viral infection." (PMID 35083168, 2021). "Lastly, as IFNs can play a role in bacterial as well as viral infections 46, we tested the susceptibility of Ddx60‐deficient mice to L. monocytogenes infection." (PMID 26457795, 2015). "DDX60 overexpression, a gene upregulated after viral infections, which has been shown to bind RIG-I, increasing RIG-I activation, decreased VSV and poliovirus replication." (PMID 36793726, 2023). "DDX60 is an antiviral helicase involved in interferon-inducible gene expression in response to viral infection." (PMID 37760054, 2023). "Virus infection stimulates DDX60 expression and promotes RLR-dependent innate immune responses, accompanied by the production of large amounts of autoantibodies, antigen-antibody reactions, and the generation of ICs." (PMID 36655136, 2023). "In the event of viral infection, phosphorylation of DDX60 can be induced by epidermal growth factor receptor (EGFR), reducing antiviral activity." (PMID 38115996, 2023). "DDX60, also present in this cluster, is known to be elevated after viral infection and promotes RIG-I-like receptor-mediated signaling." (PMID 37409113, 2023). "By constructing a PPI network, 15 hub target genes were obtained, and the top 3 node degrees were MX2 (down-regulated in MS), DDX60 (down-regulated in MS) and IRF7 (down-regulated in MS), all of which were associated with the viral infection." (PMID 36341423, 2022). "In humans, an increased expression of DDX60 has been detected following viral infections, which suggests that DDX60 is essential to initiate the innate antiviral mechanism." (PMID 31269896, 2019). "DDX3, DHX29, DHX36, and DDX60 RNA helicases have been reported to be involved in RLR-mediated type I IFN production after viral infection." (PMID 27252702, 2016). "The relationship between DDX60 expression and other different oncogenic virus infections in OSCC patients will need to be further investigated, particularly for male patients and individuals with well-differentiated OSCC." (PMID 27835882, 2016). "DDX60 is highly expressed in various viral infections and autoimmune diseases." (PMID 36655136, 2023). "Type I IFNs induce DExD/H-Box helicase 60 (DDX60) as demonstrated by viral infection-induced gene microarray analysis in human dendritic cells; DDX60 is an uncharacterized DEXD/H-box RNA helicase, similar to S. cerevisiae Ski2, a protein complex required for cytoplasmic RNA integrity." (PMID 36655136, 2023). "In addition, we detected a 25 fold increase in the abundance of DDX60 which was shown to be required for RIG-I mediated type I interferon expression after viral infection." (PMID 35281454, 2022). "However, the analysis revealed upregulation of genes involved in immune responses against viral infection, such as Ddx60 (p = 1.2 × 10–24), Dhx58 (p = 8.8 × 10–45) and Nlrc5 (p = 5.4 × 10–45)." (PMID 31620112, 2019). "Although DDX60 is involved in protection against viral infections, the clinical significance and biological function of DDX60 in cancers, particularly oral cancer, remain largely unknown." (PMID 27835882, 2016). "Next, we further assessed the role of DDX60 during viral infection." (PMID 27630638, 2016). "DDX60 is a type I interferon-inducible gene in response to viral infections." (PMID 27835882, 2016). "In addition, dozens ISGs, among which some have been characterized for their antiviral activities against various other viral infections, for example Mx1, Ifit1, Isg15, Ifi44, Ddx60, Oasl and Irf7 were up-regulated upon HDV inoculation in hNTCP-Tg mice." (PMID 25902143, 2015). "As DDX60 expression also appeared to increase binding of RNA to RIG‐I, the authors hypothesized that this helicase may bind vRNA and associate with RLRs during viral infections to enhance signaling." (PMID 26457795, 2015).
viral infection (continued). "DDX60 is a member of the DEAD-box family and was originally thought to be an antiviral protein involved in the regulation of cellular immune responses to viral infection." (PMID 40950552, 2025). "In particular, OASL binds to RIG-I and activates and enhances RIG-I signaling; OAS1 binds to viral dsRNA and, together with DDX60, helps RIG-I recognize viral RNA and amplify viral-induced RIG-I-mediated type I IFN expression after viral infection." (PMID 36655136, 2023). "IRF1 transcriptionally induced by the phosphorylated STAT1 and stabilized by XAF1 further facilitates the induction of the IRF1 target genes such as DDX58, DDX60, MX1, and OAS2 during viral infection." (PMID 35972291, 2022). "It has also been demonstrated that DDX60 is involved in the activation of the RIG-I pathway, whose receptors play a role in sensing virus infection and mediating some gene transcriptions." (PMID 36551849, 2022). "DEXD/H box helicase 60 (DDX60) is a new type of DEAD-box RNA helicase, which is induced to express after virus infection." (PMID 32765606, 2020). "DDX60, a DEXD/H box RNA helicase similar to Saccharomyces cerevisiae Ski2, is induced after viral infection." (PMID 28202761, 2017). "DDX60 and its highly similar homolog DEAD box polypeptide 60-like (DDX60L) have recently been described as interferon-stimulated products upon a viral infection." (PMID 27835882, 2016). "Here, we sought to investigate the role of DDX60 in IFN‐α/β induction and in resistance to virus infection." (PMID 26457795, 2015). "DDX60, a novel DEAD box RNA helicase, is induced after a virus infection." (PMID 27835882, 2016). "To investigate whether DDX60 might be necessary for host defense from infection despite its lack of involvement in IFN induction, we turned to a select number of murine viral infection models." (PMID 26457795, 2015). "DDX60 positively regulates DDX58 and IFIH1-dependent type I interferon response to viral infection." (PMID 25938420, 2015). "The significant downregulation of interferon signature genes, such as Adar (DRADA), Ddx58 (RIG-I), Ddx60 (DDX60), Stat1 (STAT1), Ifih1 (MDA5), Trim25 (TRIM25), Irf7 (IRF7), and Irf9 (IRF9) in infected Cd47−/− NK cells is consistent with the impaired Cd47−/− NK cell response to viral infection." (PMID 30643501, 2018). "In mammals, DDX60 binds RIG-I and promotes RNA binding and downstream type I IFN production during viral infection but has not been studied in birds." (PMID 34804075, 2021).
breast carcinoma (6 papers, 2018 to 2024). "DExD/H-Box Helicase 60 (DDX60) is a kind of dead box RNA helicase, and breast cancer patients with low expression of DDX60 are more sensitive to radio." (PMID 34384424, 2021). "In this study, we used the information of patients with breast cancer in the TCGA database for statistical analysis and found that the breast cancer patients with low expression of DDX60 exhibited radiosensitivity." (PMID 32765606, 2020). "The upregulation of DAI/ZBP1, DDX60, and p204 was detected previously in B16.F10 melanoma cells, and this was confirmed in TS/A mammary carcinoma cells." (PMID 29721152, 2018). "However, the mRNAs of TLR3, Ifih1/MDA5, Zbp1, Ddx60 and Ifi204 were upregulated by varying degrees after poly(I:C) transfection in both mammary carcinoma and fibrosarcoma cells." (PMID 35737804, 2022). "However, there was still a lack of research on the relationship between the expression levels of DDX60 gene and breast cancer." (PMID 32765606, 2020). "In addition, the low expression of DDX60 gene may also be related to the radio sensitivity of patients with breast cancer." (PMID 38380081, 2024). "In addition, previous studies had shown that the expression of DDX60 is related to cancer, but there was still a lack of relevant research in breast cancer." (PMID 32765606, 2020).
COVID-19 (4 papers, 2022 to 2023). A disease caused by infection with severe acute respiratory syndrome coronavirus 2. "The COVID-19 dataset revealed CAMP (AUC: 0.692), LTF (AUC: 0.764), DEFA1B (AUC: 0.701), SAMD9(AUC: 0.786), GBP1(AUC: 0.757), DDX60 (AUC: 0.802), DEFA4 (AUC: 0.763), and OAS3(AUC: 0.801) that exhibited superior diagnostic capabilities." (PMID 38115996, 2023).
glioma (4 papers, 2021 to 2023). A benign or malignant brain and spinal cord tumor that arises from glial cells (astrocytes, oligodendrocytes, ependymal cells). "Moreover, miRNA193a-CM down regulated PARP9, which is shown to be overexpressed in human BC cells and promotes cell migration; as well as DDX60, an interferon-associated gene which is associated with glioma malignancy." (PMID 36230929, 2022). "Our research verified the strong association between DDX60 and glioma immune microenvironment, clarified the mechanism of DDX60, and proposed that DDX60 might become a novel biomarker for immunotherapy." (PMID 34178649, 2021). "As the nomogram could show better performance than conventional staging systems and more precise prognostic forecast in some tumors, we identified DDX60 as a prognostic marker of glioma and built a nomogram with a risk classification system." (PMID 34178649, 2021). "In conclusion, these results would widen our knowledge of the expression and prognostic value of DDX60 in gliomas." (PMID 34178649, 2021). "Herein, we assume that DDX60 is a novel immune therapeutic target for glioma and explore its prognostic value and biological function in glioma." (PMID 34178649, 2021). "DDX60 was predominantly expressed in the cytoplasm of glioma cells and expressed distinctively in different WHO grades." (PMID 34178649, 2021). "In this study, bioinformatic analysis (TCGA, CGGA, Rembrandt) illustrated the upregulation and prognostic value of DDX60 in gliomas." (PMID 34178649, 2021). "In summary, DDX60 expression was higher in glioma than in normal tissue and increased with malignant escalation of glioma." (PMID 34178649, 2021). "In this study, DDX60 was not only a prognosis prediction for glioma patients but also an indicator of the immune microenvironment of glioma and might become a novel biomarker and potential therapeutic target." (PMID 34178649, 2021). "TCGA and Rembrandt dataset analysis showed that DDX60 is overexpressed in glioma (P < 0.001)." (PMID 34178649, 2021). "Herein, we demonstrated that higher expression of DDX60 was correlated with high-grade glioma." (PMID 34178649, 2021). "In summary, DDX60 expression tends to be positively related to most infiltrating immune cells, while negatively related with CD56 dim nature killer cell in glioma." (PMID 34178649, 2021). "IHC analysis verified that DDX60 expression in normal tissue (mean IRS = 2.15, n = 20) was lower than in glioma tissue (mean IRS = 5.33, n = 49) (P < 0.0001)." (PMID 34178649, 2021). "This study demonstrated that DDX60 is highly expressed in GBM and predicts poor prognosis of glioma by the Cancer Genome Atlas (TCGA), Chinese Glioma Genome Atlas (CGGA), Repository for Molecular Brain Neoplasia Data (REMBRANDT), and Gravendeel databases." (PMID 34178649, 2021). "Furthermore, DDX60 expression tends to be positively related to multiple infiltrating immune cells, while negatively related to CD56 dim nature killer cell in glioma." (PMID 34178649, 2021). "These outcomes demonstrated DDX60 as a negative prognostic indicator in gliomas." (PMID 34178649, 2021).
pancreatic cancer (4 papers, 2021 to 2025). "In summary, DDX60 can be used as a novel biomarker related to the diagnosis and treatment of pancreatic cancer, participate in tumor proliferation, and is associated with poor prognosis in patients." (PMID 39844327, 2025). "Our analysis led to the identification of a novel biomarker, DDX60, which serves as a diagnostic and prognostic tool for pancreatic cancer." (PMID 39844327, 2025). "It was further found that the prognosis of patients with high risk of DDX60 was poor, indicating that DDX60, as a proto-oncogene, is associated with poor prognosis of patients with pancreatic cancer." (PMID 39844327, 2025). "A recent study has demonstrated that DDX60 is upregulated in pancreatic cancer, and DDX60 promotes cancer cell proliferation and is associated with poor patient survival." (PMID 39329063, 2024). "Through the results of RNA-seq analysis, GO and KEGG analysis showed that DDX60 may be associated with cell cycle in pancreatic cancer." (PMID 39844327, 2025). "Furthermore, DDX60 has been linked to the immune infiltration and tumor immune microenvironment in patients, suggesting its involvement in biological processes related to tumor immune dynamics in pancreatic cancer." (PMID 39844327, 2025). "Through molecular biology experiments (MTT, LDH, and clonal formation experiment), we found that When DDX60 is knocked down in pancreatic cancer cells, the proliferation ability of tumor cells is significantly decreased." (PMID 39844327, 2025). "In conclusion, our work positions DDX60 as a significant biomarker for the diagnosis and prognosis of pancreatic cancer, with implications for developing targeted therapies." (PMID 39844327, 2025). "Through an in-depth analysis of sequencing data from the TCGA and GEO databases, we have identified DDX60, a member of the DExD/H-box RNA helicase family, as a significant biomarker in pancreatic cancer." (PMID 39844327, 2025). "In order to study the key genes of DDX60 in the biological role of cell cycle in pancreatic cancer, we imported 990 genes into the online database." (PMID 39844327, 2025). "Molecular biology experiments, including MTT, LDH, EDU, and clonal formation assays, have provided further evidence that the knockdown of DDX60 can effectively inhibit the proliferation of pancreatic cancer cells." (PMID 39844327, 2025). "Firstly, we explored the mRNA expression of DDX60 between pancreatic cancer groups and normal control groups in five GEO datasets respectively." (PMID 39844327, 2025). "By analyzing the GSE71729, GSE183795, GSE16515, GSE28735 and GSE62452 data sets, we found that DDX60 was highly expressed in pancreatic cancer." (PMID 39844327, 2025). "By MTT assay, we found that the proliferative ability of pancreatic cancer cells with DDX60 knockdown was inhibited." (PMID 39844327, 2025). "From the results, we learned that the expression level of DDX60 in pancreatic cancer was significantly higher than that in normal tissues and was statistically significant." (PMID 39844327, 2025). "Our findings demonstrate a significant correlation between elevated DDX60 expression and a poor prognosis in patients with pancreatic cancer." (PMID 39844327, 2025). "From the CPTAC database, we know that the protein level of DDX60 is significantly higher in pancreatic tumor tissues than in normal tissues." (PMID 39844327, 2025). "In summary, we reveal the biological pathway of DDX60 involvement in pancreatic cancer." (PMID 39844327, 2025). "The GEPIA database again verified that DDX60 was highly expressed in pancreatic cancer (P < 0.05)." (PMID 39844327, 2025). "Furthermore, we have established that DDX60 is overexpressed at both the transcriptome and protein levels in pancreatic cancer, marking it as a prognostic indicator of poor outcomes." (PMID 39844327, 2025). "In order to investigate whether DDX60 knockdown can inhibit the proliferation of pancreatic cancer cells, we knockout DDX60 in Panc02 cells." (PMID 39844327, 2025).
pancreatic cancer (continued). "We performed RNA-seq to further explore the downstream biological targets of DDX60 and the signaling pathways that may be involved in pancreatic cancer." (PMID 39844327, 2025). "From our study, we know that DDX60 is highly expressed in pancreatic cancer at both RNA and protein levels (P < 0.05), indicating that DDX60 may be a proto-oncogene driving the formation of pancreatic cancer." (PMID 39844327, 2025). "But there is no report of DDX60 involvement in pancreatic cancer, in spite of its consistent upregulation." (PMID 34912796, 2021).
colorectal cancer (3 papers, 2021 to 2022). A primary or metastatic malignant neoplasm that affects the colon or rectum. "The expression of DDX60 is related to the stage of cancer and has a potential key to the diagnosis, prognosis, and treatment of colorectal cancer (CRC)." (PMID 34384424, 2021). "DDX60 is a DEAD-box RNA helicase and has been proved upregulated in melanoma and oral squamous cell carcinoma (OSCC) while deregulating in colorectal cancer." (PMID 34178649, 2021).
melanoma (3 papers, 2018 to 2021). A malignant, usually aggressive tumor composed of atypical, neoplastic melanocytes. "By analyzing the TCGA genomics, we also found that the gene alteration rates in the melanoma TCGA dataset were 12% for DDX60, 5% for CSNK1E, 2.8% for FGD1, 2.1% for GBP4, 4% for IFIH1, 1% for DOK1, and 0.7% for IRX3, and these alterations were not significantly correlated with mRNA expression." (PMID 34769455, 2021). "We also found that the overexpression of GBP4, DOK1, DDX60, and IFIH1 is correlated with better overall survival in several melanoma datasets." (PMID 34769455, 2021). "Although higher transfection efficiency was obtained in WEHI 164 cells, similar sensors (DAI/ZBP1, DDX60 and p204) were upregulated in two cell lines TS/A and WEHI 164 as in our previous study on B16F10 melanoma cells." (PMID 29721152, 2018).